RNU6-531P (RNA, U6 small nuclear 531, pseudogene)
Gene: Small nuclear RNA gene on chromosome 4 (139,055,475 to 139,055,578, forward strand). Ensembl gene ENSG00000252503.
Homologues: Orthologues: chimpanzee U6 (99% identical), macaque U6 (88% identical), dog U6 (71% identical). Paralogues in human: RNU6-1145P (82% identical), RNU6-1209P (82% identical), RNU6-1329P (82% identical), RNU6-216P (82% identical), RNU6-218P (82% identical), RNU6-86P (82% identical), RNU6-11P (81% identical), RNU6-23P (81% identical), RNU6-33P (81% identical), RNU6-37P (81% identical), RNU6-38P (81% identical), RNU6-47P (81% identical), and 1286 more.